INS (insulin)
Diseases named in the same sentence as INS in open-access papers (continued):
Sharing a sentence is not in itself a finding about the gene and the disease.
hypertriglyceridemia (continued). "Excess visceral fat is strongly associated with impaired suppression of FFA release in response to insulin, as well as with hypertriglyceridemia and low concentrations of high density lipoprotein (HDL) cholesterol." (PMID 23434905, 2013). "For example, leptin deficiency is associated with hypertriglyceridemia, low HDL C, and low insulin sensitivity in cases of acquired or congenital lipodystrophies; leptin therapy reverses the metabolic dysfunction." (PMID 23533722, 2013). "The depressed activity of insulin-mediated lipoprotein lipase (LPL) made the clearance rate of lipoprotein descend, which is the main cause of hypertriglyceridemia in T2DM disease." (PMID 21716678, 2012). "While specific therapies like heparin and insulin infusion are indicated in hypertriglyceridemia-induced acute pancreatitis, the American Society of Apheresis guidelines have approved the use of therapeutic plasmapheresis in the setting of worsening systemic inflammation or lactic acidosis." (PMID 41234997, 2025). "However, she was readmitted at 23 weeks' gestation with recurrent hypertriglyceridemia (2872 mg/dL, 32.4 mmol/L), requiring a more aggressive insulin regimen." (PMID 39949380, 2025). "With the progression of IR, impaired insulin signaling in adipocytes leads to increased lipolysis and elevated circulating free fatty acids, which further exacerbate hepatic very-low-density lipoprotein production and hypertriglyceridemia." (PMID 41019320, 2025). "While IV insulin remains a first-line therapy, heparin is no longer recommended due to rebound hypertriglyceridemia and the risk of bleeding." (PMID 41393592, 2025). "IPA networks from the phosphoproteome showed relevance to highly similar canonical pathways, such as those related to lipoprotein and cholesterol metabolism, hypertriglyceridemia, weight gain and to the quantity of insulin in the blood, to be important in both conditions." (PMID 41441338, 2025). "However, when comparing the two main treatment options for HLAC, insulin infusion is increasingly preferred over plasmapheresis for managing severe hypertriglyceridemia, particularly in the context of hypertriglyceridemic pancreatitis." (PMID 39958046, 2025). "Thus, in acute settings such as the ED where rapid intervention is critical, insulin infusion emerges as a safer and more clinically beneficial option for managing hypertriglyceridemia, as was observed in our patient’s case." (PMID 39958046, 2025). "This led to a suspicion of hypertriglyceridemia‐induced pancreatitis requiring an insulin infusion." (PMID 41473820, 2025). "Progressive decrease in peripheral insulin sensitivity, together with and mediated by a higher concentration of estrogen are thought to be responsible for hypertriglyceridemia, impaired suppression of glucose production, and impaired stimulation of glucose utilization." (PMID 39506943, 2024). "Our patient was treated with an insulin infusion for hypertriglyceridemia." (PMID 39011188, 2024). "Insulin therapy, together with diet modification and other supportive measures, provides effective control of hypertriglyceridemia, which reduces the chances of pancreatitis in the future as well as other severe complications, thus improving both fetal health status and maternal condition." (PMID 39457565, 2024). "Additionally, visceral fat-derived hypertriglyceridemia increases the free fatty acid levels hepatically, which reduces insulin sensitivity and raises the hepatic glucose output." (PMID 39519551, 2024). "In addition to pain management and stabilization of electrolyte abnormalities, treatment of acute pancreatitis secondary to hypertriglyceridemia should focus on intravenous fluids and insulin." (PMID 39574983, 2024). "These mothers probably require supraphysiological insulin doses to maintain glycemic control and prevent hypertriglyceridemia and resultant pancreatitis; this titration strategy could impact the final baby weight or polyhydramnios presence." (PMID 39479521, 2024).
hypertriglyceridemia (continued). "Elevated serum glucose and insulin concentrations are known to promote hypertriglyceridemia." (PMID 37990256, 2023). "Notably, ectopic expression of STK38 in mouse liver leads to lean NAFLD phenotype with hepatic inflammation, insulin resistance, intrahepatic lipid accumulation, and hypertriglyceridemia in mice fed on a regular chow diet." (PMID 37028764, 2023). "In addition, mean fasting insulin fell (mean fasting insulin, 23 mU/L at baseline; after seven weeks, 12 mU/L); after seven weeks the insulin secretory response after an oral glucose load was improved, while the hypertriglyceridemia normalized." (PMID 36901984, 2023). "Furthermore, a weak adherence to diet is associated with alteration in several cardiometabolic outcomes (hypercholesterolemia and hypertriglyceridemia, insulin resistency, elevated blood pressure)." (PMID 38188871, 2023). "However, there are few clinical studies on the treatment of severe hypertriglyceridaemia with insulin in the third trimester of pregnancy." (PMID 36405614, 2022). "Insulin infusion should be considered in case of hypertriglyceridemia induced acute pancreatitis." (PMID 35637980, 2022). "In a normal state, it was reported that insulin activates lipoprotein lipase, which hydrolyzes triglycerides, however, in a diabetic state, the enzyme’s inactivation may result in hypertriglyceridemia." (PMID 35308202, 2022). "Hypertriglyceridemia has been related to impaired insulin action and β-cell function in pregnancy." (PMID 35745231, 2022). "Therefore, we concluded that insulin was effective in treating severe hypertriglyceridaemia in the third trimester of pregnancy." (PMID 36405614, 2022). "The effect of choline and betaine composition on lower HS-OR remained significant after adjustment for VOB and metabolic dysfunction markers of hypertriglyceridemia (indicating abnormal hepatic and systemic lipid metabolism) and insulin resistance (indicating hepatic energy metabolism regulation)." (PMID 35057441, 2022). "From our results in over 380 individuals, we harmonized cutoffs for postprandial insulin sensitivity and hypertriglyceridemia with reported cut-points using OGTTs and meal challenge tests, while evaluating the intra- and inter-individual variability in responses." (PMID 35634390, 2022). "BJ supplementation for 14 weeks counteracted diet-evoked metabolic deregulation, improving glucose tolerance, insulin sensitivity, and hypertriglyceridemia, along with systemic and hepatic antioxidant properties, without a significant impact on the gut microbiota composition and related mechanisms." (PMID 34959746, 2021). "In addition, the increased mRNA levels of Apoc3, which is usually downregulated by insulin, reasserts some degree of IR in the liver contributing to hypertriglyceridemia by the diminished TG hydrolysis by the LPL." (PMID 34202724, 2021). "It is also highly probable that the observed hypertriglyceridemia was a results of reduced lipoprotein lipase (LPL) activity as a result of insulin decrease in our study (LPL is responsible for the triglyceride-rich lipoprotein hydrolysis and is activated by insulin)." (PMID 35050980, 2021). "After considering these reports, and in light of our previous finding that insulin can stimulate secretion of ANGPTL3/8 from hepatocytes, we hypothesized that LXR agonists might cause hypertriglyceridemia by stimulating hepatic secretion of ANGPTL3/8." (PMID 33762177, 2021). "Moreover, hypertriglyceridemia was reported to diminish glucose stimulated insulin secretion by inhibiting glucose oxidation via reducing pyruvate dehydrogenase (PDH) activity and elevating PDH kinase activity." (PMID 34134670, 2021). "Although presenting normal food intake as compared to other experimental groups, the LS diet groups showed increased body mass, a clinical condition that is in many cases accompanied by insulin signaling impairment, hypertriglyceridemia, and liver fat accumulation." (PMID 34202724, 2021).
hypertriglyceridemia (continued). "The fact that HOMA-IR and fasting insulin where higher and more variable in the patient group indicates that some of the patients were insulin-resistant, which is to be expected in a group of patients suffering from mild to moderate hypertriglyceridemia." (PMID 34065380, 2021). "This could be explained by an impaired binding of insulin to its receptors and/or stem from hypertriglyceridemia, which may impair insulin signal transduction." (PMID 33233346, 2020). "FGF21 is reported to improve insulin sensitivity and hypertriglyceridemia." (PMID 32584895, 2020). "If, indeed, hypertriglyceridemia is pathological in humans, whether and how to intervene remains unclear, with ongoing debate around the use of intravenous insulin infusion and lipid apheresis." (PMID 33291273, 2020). "However, hyperinsulimia and hypertriglyceridemia significantly elevated insulin levels, and plasma TG levels, as compared to age/sex-matched young animals." (PMID 31246177, 2019). "In fact, hypertriglyceridemia leads to elevated levels of free fatty acids (FFAs), which contribute to insulin resistance and β-cell dysfunction, putatively by impairing the molecular mechanisms linking insulin receptors with glucose transporters, as well as by directly damaging β-cells." (PMID 28635632, 2017). "This low level of insulin promotes hypertriglyceridemia and secretion of VLDL cholesterol." (PMID 26927161, 2016). "However, there is lack of clinical evidence supporting the effects of lowering TG for insulin sensitivity and β-cell function in hypertriglyceridemia patients with normal glucose tolerance." (PMID 27034649, 2016). "Our data suggest that the treatment with RSV + QRC tends to decrease the PUFAs in MetS rats, and this might stimulate the decrease in hypertriglyceridemia, thus contributing to a reduction in adipocyte hypertrophy and an increase in insulin sensitivity." (PMID 27399675, 2016). "The restoration of insulin sensitivity, in turn, may account for the improvement in lipid profile, i.e., reduction in hypercholesterolemia and hypertriglyceridemia and increased HDL-C." (PMID 26247970, 2015). "The hypertriglyceridemia observed after ApoA5 knockdown might lead one to hypothesize that ApoA5 knockdown would diminish tissue insulin sensitivity." (PMID 25548259, 2015). "Hypertriglyceridemia, FFAs overload and lipid accumulation in non-adipose tissues influence both insulin action and insulin secretion and are frequently associated with IR and the development of T2DM." (PMID 25471221, 2014). "Thus, in individuals with both insulin sensitivity and hypertriglyceridemia, the excess of lipids seems to be stored, lipid oxidation inhibited and RQ increased." (PMID 24566437, 2014). "Insulin is also used clinically to treat hypertriglyceridemia-induced pancreatitis." (PMID 24993827, 2014). "Taken as a whole, these data suggest that RBP4 may play a role in the pathophysiology of hypertriglyceridemia in insulin-resistant states." (PMID 24223837, 2013). "The acidosis and hypertriglyceridemia resolved with intravenous insulin therapy and rehydration." (PMID 23748069, 2013). "Several in vivo and in vitro studies have shown that hypertriglyceridemia diminishes glucose-induced insulin secretion via the glucose–fatty acid cycle in which fatty acid oxidation inhibits glucose oxidation by decreasing pyruvate dehydrogenase (PDH) activity and increasing PDH kinase activity." (PMID 22876749, 2012). "In one study on human LPL-deficient subjects, enhanced glucose-stimulated insulin secretion after an oral glucose tolerance test was found, compared to other groups of non-diabetic patients with hypertriglyceridemia." (PMID 23186339, 2012). "This fact could be explained either by recurrent pancreatitis episodes linked to hypertriglyceridemia, thus leading to insulin secretion impairment, or to an adaptive mechanism of the glucose receptor, GLUT2, for reducing the secretion of insulin." (PMID 22284844, 2012).
hypertriglyceridemia (continued). "Hypertriglyceridemia - another IR-inducer - was also present in these rats due to a combined effect of excess FA provision to the liver, decreased esterification in adipose tissue, and attenuation of the lowering effect of insulin on hepatic VLDL secretion." (PMID 20964827, 2010). "Hypertriglyceridemia observed in T1DM patients may be attributed to increased VLDL production secondary to relative insulin deficiency and decreased lipoprotein lipase activity in patients inadequately treated with insulin." (PMID 40076685, 2025). "Ramipril or simvastatin alone do not increase lifespan in mice, but the combination of these medications significantly extends lifespan Simvastatin may blunt insulin sensitivity, while both simvastatin and ramipril induce hypercholesterolemia and hypertriglyceridemia." (PMID 38966557, 2024). "Finally, even if sufficiently high systemic levels of SCFAs are reached, it will be essential to prevent comorbidity-related adverse effects such as hyperphagia, hypertriglyceridemia, ectopic lipid deposition in liver and skeletal muscle, and liver and muscle insulin resistance." (PMID 35811951, 2022). "Therefore, the reduction of the small and the increase in the large adipocytes observed in the MO group may be associated with increased insulin serum levels and HOMA index as well as hypertriglyceridemia and liver fat accumulation." (PMID 36290594, 2022). "Moreover, hypertriglyceridemia has adverse effects on insulin sensitivity and islet beta-cell function, which might affect glycemic control." (PMID 34126706, 2021). "High GI and GL have been considered to exacerbate postprandial hypertriglyceridemia, especially when fructose was administered, but contradictions have also been observed when lower doses were used or due to different food components and metabolic conditions such as insulin resistance." (PMID 32722053, 2020). "Serum parameters evidenced the development of hypertriglyceridemia (2.6-fold increase in serum triglycerides levels); and a significant increase in the TG-to-HDL-C ratio, which is indicative of a higher degree of cardio-metabolic risk in the insulin-resistant condition." (PMID 31114513, 2019). "However, the safety and efficacy of heparin and insulin in the treatment of hypertriglyceridemia-associated acute pancreatitis have not been well established yet." (PMID 28225998, 2017). "Furthermore, fructose-induced insulin resistant rats treated with extracts of Angelica keiskei, Panax ginseng root, and the root of Acanthopanax senticosus were found to have improved insulin sensitivity and hypertriglyceridemia." (PMID 27322374, 2016). "In the insulin resistant state, the normal suppression by insulin of free fatty acid release from adipose tissue is impaired so that the characteristic diabetic dyslipidemia occurs, i.e. hypertriglyceridemia, low HDL-cholesterol concentrations and elevation of free fatty acids." (PMID 23185996, 2012). "Therefore the observed diminution of VLDL and the hypertriglyceridemia by α, β-amyrin might be a result of improved insulin sensitivity." (PMID 22867128, 2012). "Thus, insulin levels are involved in hypertriglyceridaemia after meals." (PMID 21162746, 2010). "Her severe hypertriglyceridemia prompted admission to the intensive care unit (ICU) for aggressive isotonic fluids, weight‐based IV insulin infusion, and serial labs." (PMID 41393592, 2025). "Heparin, when used in combination with insulin, releases stored LPL to reduce triglyceride levels but carries risks such as rebound hypertriglyceridemia and hemorrhage with continuous use." (PMID 40432658, 2025). "A review of his chart revealed a prior admission two years ago, in June 2021, for hypertriglyceridemia-induced pancreatitis and DKA treated with insulin drip." (PMID 39144851, 2024). "In dogs, the development of hypertriglyceridemia is promoted by an increased supply of substrates to the liver, especially glucose and FFA, in insulin-resistant states." (PMID 39296580, 2024).
hypertriglyceridemia (continued). "Because insulin has an impact on how vLDL-C and HDL-C are metabolized, patients with IR frequently exhibit hypertriglyceridemia and low HDL-C levels." (PMID 37520476, 2023). "This apolipoprotein reflects insulin sensitivity and negatively modulates LPL activity driving plasma levels of triglycerides and being a target of drugs for hypertriglyceridemia control." (PMID 36899434, 2023). "In fact, synthetic PPAR-α agonists, such as fibrates, are drugs currently in use for the clinical treatment of hypertriglyceridemia, while PPAR-γ agonists, including thiazolidinediones (TZDs), are known as insulin-sensitizing drugs." (PMID 35203272, 2022). "Insulin normally suppresses hepatic production of very low-density lipoprotein (VLDL), which is rich in triglycerides; thus, insulin resistance leads to hypertriglyceridemia." (PMID 31993196, 2020). "Her insulin regimen was continued after resolution of DKA, and her pancreatitis with hypertriglyceridemia showed resolution." (PMID 30891384, 2019). "Reduced plasma insulin concentrations prevent very low-density lipoprotein (VLDL) synthesis, which can lead to hypertriglyceridemia." (PMID 31817748, 2019). "In insulin resistant status, failure to inhibit MPL and activate LPL would lead to hypertriglyceridemia." (PMID 31794594, 2019). "We conclude that saroglitazar effectively reduces hypertriglyceridemia and improves insulin sensitivity along with β-cell function by reduction in gluco-lipotoxicity and possibly directly through PPAR-γ agonism in patients ofT2DM with hypertriglyceridemia." (PMID 31831868, 2019). "Most participants had total cholesterol (TC) and LDL-c concentrations within the normal range but 33% had hypertriglyceridemia, 44% had low plasma HDL-c and 77% had fasting plasma insulin ≥90 pmol/l, with women being more likely to be affected." (PMID 27427488, 2016). "Heparinization was also reported as an alternative treatment for hypertriglyceridemia in adult DKA patients, together with fluid and insulin administration." (PMID 26904318, 2016). "In most cases, patients with IR have hypertriglyceridemia and low HDL-C levels because insulin affects the metabolism of very low-density lipoprotein cholesterol (VLDL-C) and HDL-C." (PMID 26146523, 2015). "Secondly, our finding that the associations between these amino acids and hypertriglyceridemia persisted after excluding patients with T2D does not mean that the mechanisms are unrelated to insulin sensitivity (which may be present among non-diabetic subjects)." (PMID 24682914, 2014). "The known effects of CHO-induced hypertriglyceridemia, the HDL-lowering effect of low fat, high CHO interventions and the obvious improvement in glucose and insulin from CHO restriction should have made this evident." (PMID 16288655, 2005). "Insulin regulates the production of very low‐density lipoprotein (VLDL) to limit the level of plasma TGs, and consequently, the aberrant insulin effect leads to hypertriglyceridemia." (PMID 40084433, 2025). "The non-diabetic ketoacidosis protocol was initiated with insulin at 1 unit/hour to treat hypertriglyceridemia." (PMID 39011188, 2024). "None of these patients required plasmapheresis or insulin infusion as a treatment for hypertriglyceridemia." (PMID 36819167, 2023). "We present a rare case of a 52-year-old male with asymptomatic severe hypertriglyceridemia exceeding 11,000 mg/dL, managed initially with oral therapy without the need for an insulin drip or plasmapheresis." (PMID 37790029, 2023). "At 30 weeks of age, male, but not female, Akr1d1–/– mice were more insulin tolerant and had reduced lipid accumulation in the liver and adipose tissue yet had hypertriglyceridemia and increased intramuscular triacylglycerol." (PMID 35318963, 2022).